LINC00847 (long independently transcribed non-coding RNA 847)
Gene: Long non-coding RNA gene on chromosome 5 (180,830,326 to 180,839,742, forward strand). Ensembl gene ENSG00000245060.
Diseases named in the same sentence as LINC00847 in open-access papers:
LINC00847 is named in the same sentence as 6 diseases in open-access papers, as found by Europe PMC text mining. Sharing a sentence is not in itself a finding about the gene and the disease. The quoted sentences say what the papers report.
breast carcinoma (2 papers, 2022). "In recent years, aberrant expression of LINC00847 has been reported in various tumors including renal cell carcinoma, breast cancer and lung cancer." (PMID 36211292, 2022). "Expression analyses and ROC curves were performed using mRNAs co-expressed with CTD-2566J3.1 and LINC00847 in samples from patients with luminal B-type breast cancer." (PMID 36359853, 2022).
lymph node metastasis (2 papers, 2022 to 2024). "High LINC00847 expression was associated with poor differentiation and lymph node metastasis." (PMID 35435130, 2022). "Additionally, elevated LINC00847 levels are correlated with lymph node metastasis and poor differentiation, suggesting its potential as a prognostic biomarker." (PMID 38589454, 2024).
cancer (6 papers, 2021 to 2024). A tumor composed of atypical neoplastic, often pleomorphic cells that invade other tissues. "Mechanistically, LINC00847 is induced by the transcription factor E2F, exerting its influence on cancer progression through the modulation of downstream targets, including miR-147a24." (PMID 38589454, 2024). "Notably, LINC00847 has been extensively studied in various cancer types." (PMID 38589454, 2024). "Finally, both LINC00847 and CTD -2566J3.1 were co-expressed with essential genes for cancer genetic dependencies, such as FOXA1 y GINS2." (PMID 36359853, 2022). "In this study, several ARlncRNAs included in the modeling process have been already reported in various malignant tumors, such as CARD8-AS1, AC060780.1, AC123595.1, UGDH-AS1, LINC00996, LINC00861, AL606489.1, HLA-DQB1-AS1, LINC00654, and LINC00847." (PMID 34956321, 2021). "To explore the effects of miR-147a in the mechanisms and functions of LINC00847, we next sought to discover the downstream target of miR-147a using starbase algorithm, and found that IFITM1, a well-known oncogene in diverse cancer types, might be the possible target." (PMID 33968966, 2021). "The roles of LINC00847 and LINC01184 have not been reported in HCC, but several studies have demonstrated that they have a carcinogenic effect in many other cancers." (PMID 35627170, 2022).
tumor (2 papers, 2022 to 2024). "The results of the in vivo experiment showed that LINC00847 knockdown suppressed TU212 cell xenograft tumor growth in nude mice, while overexpression of ZEB2 counteracted this effect." (PMID 35435130, 2022). "LINC00847 positively correlates with the infiltration of various immune cell types, and its overexpression significantly down-regulates PDL1 expression in the in-vitro assay, thus casting it as a prospective candidate in tumor immunotherapy." (PMID 38589454, 2024). "LINC00847 was mainly located in the cytoplasm of LSCC cells, and LINC00847 overexpression promoted LSCC cell proliferation, migration, invasion, and accelerated the cell cycle progression while knocking down LINC00847 had the opposite effects in vitro and inhibited the tumor growth in vivo." (PMID 35435130, 2022).
LINC00847 also shares sentences with these, for which no sentence is quoted: lung carcinoma (1 paper); renal cell carcinoma (1).